MITF (melanocyte inducing transcription factor)
Diseases named in the same sentence as MITF in open-access papers (continued):
Sharing a sentence is not in itself a finding about the gene and the disease.
melanoma (continued). "Although the mRNA expression of MITF was elevated in both melanoma cell lines following PACAP treatment, a significant reduction was detected in melanocytes." (PMID 41465475, 2025). "The KIT receptor tyrosine kinase and the transcription factor MITF, both amplified in 10–20% of melanomas were also considered." (PMID 40647405, 2025). "Based on the results of in vitro experiments with B16F10 melanoma cells, 10 μM FKCNFs repressed the expressions of melanogenesis-related proteins MITF and TRP2." (PMID 40243614, 2025). "In melanoma, MITF protein functions as a transcription factor involved in proliferation and differentiation." (PMID 40981345, 2025). "In melanoma, MITF exhibits oncogenic properties, with gene amplification occurring in approximately 20% of cases, thereby facilitating tumor cell proliferation." (PMID 40427124, 2025). "The results of this study provide valuable insights into the role of MITF expression in melanoma and its relationship with TILs." (PMID 39976551, 2025). "NAT10 promotes malignant melanoma growth through MITF/cyclinD1/CDK2/p21-mediated cell cycle progression." (PMID 40588654, 2025). "AMBLor positivity has been associated with reduced recurrence risk in early-stage melanoma, while data for YB-1, TRPM1, and MITF continue to emerge." (PMID 40981345, 2025). "Eight (10%) patients were identified that carried pathogenic mutations in known melanoma predisposition genes POT1, MITF, OCA2, SLC45A2 and TYR." (PMID 39315505, 2025). "We therefore used 501mel human melanoma cells, in which we previously mapped genome-wide binding of MITF,64,72 to express Dox-inducible hemagglutinin (HA)-tagged TFEB and performed ChIP-seq using the highly specific HA antibody." (PMID 41275493, 2025). "Among these, two overlapping targets (TYR and MITF) were considered potential targets for the treatment of melanoma." (PMID 40708947, 2025). "Overall, fisetin acts as a negative regulator of melanogenesis in human melanoma cells by lowering intracellular tyrosinase levels and inhibiting MITF expression." (PMID 41373883, 2025). "MITF, a master regulator of melanogenesis and a melanoma oncogene, has also been reported to regulate the immunosuppressive functions of myeloid-derived suppressor cells (MDSCs) in a mouse model." (PMID 40894019, 2025). "LncRNA components of the MITF network are thus predicted to be important regulators of melanocyte development and melanoma biology." (PMID 41336739, 2025). "In conclusion, our study firstly showed that SPEF suppressed α-MSH-induced melanogenesis by modulating the PKA/CREB/MITF signaling pathway in B16F10 melanoma cells and a zebrafish model." (PMID 40003988, 2025). "When stratified by Breslow thickness, melanomas <1.5 mm had a median MITF expression of 24% (95% CI: 2%–68%), while those >1.5 mm had a median of 33% (95% CI: 12%–92%), a statistically significant difference (P ═ 0.032)." (PMID 39976551, 2025). "Compared to C3, C1/C2/C4 subpopulations showed higher metastasis feature, including melanoma invasion marker genes MITF and PMEL, which were highly expressed in C1/C2." (PMID 40866912, 2025). "MITF is a transcription factor specific to the melanocytic lineage, which plays a significantly expanded role in malignant melanoma." (PMID 40872623, 2025). "To determine the intracellular effects of the combination in melanoma cells, we investigated the effects of combination treatment on the ERK1/2 signaling pathway and subsequently on MITF, which is critical for melanoma cells." (PMID 40063190, 2025). "This disruption leads to attenuation of MITF-mediated gene expression, thereby suppressing melanoma cell growth." (PMID 40807231, 2025). "The unsupervised analysis revealed a more nuanced reflection of melanoma de-differentiation than a single trend of MITF high to MITF low melanoma cells." (PMID 38183207, 2025). "MITF has attracted considerable attention for its multifaceted role in cellular physiology, particularly in melanoma." (PMID 41168571, 2025).
melanoma (continued). "This suggests that human and zebrafish DANCR are conserved components of the MITF network in melanocyte development and melanoma." (PMID 41336739, 2025). "MITF ChIP-seq in melanoma identified targets involved in DNA replication, repair, and mitosis; however, in GISTs, our data indicate a distinct regulatory role." (PMID 41168571, 2025). "Further studies to evaluate the effect of ZDL on MITF expression in melanoma cell lines will thus be an important component of future work, although it is notable that direct treatment of cultured melanocytes with ZDL repressed melanin secretion." (PMID 40141086, 2025). "In melanoma, NAT10 silencing induces S-phase cell cycle arrest by downregulating Microphthalmia-associated Transcription Factor (MITF) expression, significantly suppressing tumor cell proliferation in both in vitro and in vivo experimental systems." (PMID 40881352, 2025). "The expression of MITF in melanoma is often biphasic; both high and low levels can contribute to melanoma progression through different mechanisms." (PMID 41465475, 2025). "In this context, recent studies indicate that MITF plays a role in regulating ferroptosis in melanoma cells, acting primarily as a protective factor by modulating genes related to lipid homeostasis and the antioxidant response." (PMID 40343114, 2025). "A finding showed that MITF, the master regulator of melanocyte differentiation, exhibits an inverse correlation with melanoma cell motility and invasiveness at lower expression levels." (PMID 40708947, 2025). "An example of melanoma-driving transcription factor is the melanocyte inducing transcription factor (MITF), overexpressed in 20% of metastatic melanomas and necessary for the survival of normal human melanocytes." (PMID 40872623, 2025). "Further, MITF is amplified in a fraction of human melanomas and has been termed a lineage survival oncogene." (PMID 40809945, 2025). "In melanotic melanoma cells, miR‐211 acts as a direct target of MITF and regulates EDEM1 expression and cell migration, subsequently impairing the degradation of Tyrosinase." (PMID 39823244, 2025). "Our network analysis identified feedback and feedforward motifs involving SOX10, MITF, miRNAs, other genes that were (differentially) expressed in melanoma." (PMID 40458894, 2025). "This was confirmed in R722W melanoma cells, where we downregulated endogenous MITF using two independent siRNAs and observed reduced REDD2 protein expression." (PMID 40918647, 2025). "HDAC inhibition has been shown to decrease MITF and suppress melanoma growth, possibly through the disruption of SE looping." (PMID 41392986, 2025). "Conversely, when lymphocytes are positioned along the edges of the melanoma, MITF protein expression is significantly lower." (PMID 39976551, 2025). "Our findings suggest that human melanoma cell lines can adopt two transcriptomically and phenotypically distinct, mutually exclusive “MITF-low” states—DEDIFF and MYC." (PMID 41405996, 2025). "Genome-wide analyses of melanoma cells have confirmed that MITF target genes are enriched for pathways involved in DNA replication, repair, and mitosis, underscoring its central role in oncogenesis." (PMID 41168571, 2025). "Collectively, these observations underscore the pivotal roles of miRNAs and SOX10 in regulating phenotype switching, frequently through pathways involving MITF, emphasizing their intricate interplay in melanoma plasticity." (PMID 40458894, 2025). "When ATF2 activity is low, SOX10 is highly expressed (phase 1‐ON), leading to high miR‐204 and MITF levels that make melanoma cells show a melanocytic or intermediate phenotype." (PMID 40458894, 2025). "MITF thus regulates DANCR in a melanoma cell dependent manner whilst c-MYC activates DANCR across melanoma cells." (PMID 41336739, 2025).
melanoma (continued). "By contextualizing our findings within the existing literature, we underscore the need for further investigation into MITF and related pathways to enhance melanoma management and improve patient outcomes." (PMID 39976551, 2025). "We detected miTF and Ki-67 in melanoma tissues and found that the miTF and Ki-67 were downregulated in the salidroside-treated group." (PMID 40708947, 2025). "Archival formalin-fixed, paraffin-embedded tissue samples from 81 primary melanoma patients were analyzed via tissue microarray immunohistochemistry to assess MITF protein levels." (PMID 39976551, 2025). "When BRAF or MEK is inhibited, the feedback mechanisms in melanoma cells trigger compensatory pathways to reactivate or increase MITF expression." (PMID 40872623, 2025). "MITF is crucial for regulating genes involved in melanocyte development, pigmentation, and the progression of melanoma." (PMID 40807231, 2025). "SIRT5 modulates histone acetylation and methylation, maintaining the expression of critical genes such as MITF and c-Myc, thus promoting melanoma cell survival and representing a genotype-independent therapeutic vulnerability." (PMID 40573249, 2025). "A recent in vivo study using a zebrafish melanoma model showed that MITF regulates the antioxidant program, thereby increasing the survival of melanoma cell lines by protecting the cells from damage induced by ROS." (PMID 39940783, 2025). "It is plausible that melanoma cells at varying stages of differentiation will show different responses to the combination of MITF knockdown and IFNγ stimulation." (PMID 39736644, 2024). "A fluid state between MITF-high and MITF-low melanomas, presumably at least partially in response to different environmental triggers, has been proposed as a rheostat-like modulation model." (PMID 39277608, 2024). "In the melanomas with simultaneous deletion of MITF and PTEN, there is a more obvious reduction of T cell recruitment." (PMID 38835341, 2024). "Immunofluorescence analyses were conducted on B16 melanoma cells using antibodies to β-catenin (green) or MITF (red)." (PMID 38920996, 2024). "While MITF and other TFs are essential for the development and homeostasis of the melanocyte lineage, they also play important roles during melanoma initiation and progression, and they are well characterized during phenotype switching." (PMID 38319712, 2024). "Effects of TPC2 or Rab7a KO or KD on proliferation, migration, and invasion were seen particularly in melanoma lines expressing high levels of MITF, and MITF levels were strongly depleted or reduced after either KO or KD of TPC2 or Rab7a." (PMID 39562548, 2024). "During melanogenesis, α-MSH induction of MITF was mediated by a decrease in small heterodimer partner-interacting leucine zipper protein expression in B16F10 mouse melanoma cells." (PMID 38920996, 2024). "In contrast to MITFhigh (MITF+) melanoma cells, which in general are responsive to RAF and MEK inhibitors, melanoma cells expressing high levels of AXL are associated with resistance." (PMID 39697983, 2024). "This evidence prompted us to apply an unbiased approach to elucidate the extent of MITF-regulated expression of redox-related genes in melanoma cells." (PMID 39277608, 2024). "Based on these observations, further studies are needed to confirm the reliability of the MITF/ABCB5 axis as a marker of melanoma cell stemness." (PMID 39199632, 2024). "Here, the authors show that Rab7a enhances the activity of TPC2 to promote melanoma progression through the GSK3β/β-Catenin/MITF axis." (PMID 39562548, 2024). "Fluorescence microscopy showed that 10E-PDA treatment inhibited α-MSH-induced nuclear translocation of MITF in B16F10 melanoma cells, with a similar inhibitory effect at the same concentration as α-linolenic acid, a fatty acid known for its whitening effect." (PMID 39765875, 2024). "This is in agreement with previous data indicating that MITF low levels are correlated with the induction of senescence in melanoma." (PMID 38472212, 2024).
melanoma (continued). "Similar findings were noted in Cancer Cell Line Encyclopedia (CCLE) melanoma cell lines (n = 25) and an anticorrelation between MITF and ITGA3 was present (P = 0.002, OR, –0.54)." (PMID 38319712, 2024). "It is important to mention that MITF involvement in the development of resistance to targeted therapies in melanoma is challenged by some contradictory results depicting it as either an antagonist or facilitator of resistance." (PMID 38472212, 2024). "Currently, technological advances have allowed the identification of additional genes involved in melanoma susceptibility: BRCA2, BAP1, and MITF." (PMID 38473275, 2024). "Recent studies have found that the PPAR family induces enhanced melanogenesis in melanocytes and melanoma cells by affecting the melanocyte-stimulating hormone receptor (MC1R) and melanocyte-associated transcription factor (MITF) signaling pathways." (PMID 38159176, 2024). "In melanoma, MITF activity mediates phenotype plasticity such that high MITF activity promotes differentiation and proliferation, whereas low MITF activity results in a stem cell-like phenotype and enhances migration." (PMID 39169200, 2024). "MITF silencing has been also performed in two BRAF-wild type melanoma cells, namely SKMEL2 and VMM917 cells." (PMID 38472212, 2024). "Increased secretion of IL-8 and CXCL11 following MITF knockdown alone are a novel finding in melanoma." (PMID 39736644, 2024). "•MITF+ melanoma subpopulations significantly decreased upon immunotherapy, and inversely correlated with T cell infiltration." (PMID 39697983, 2024). "While some melanoma cell lines investigated here express high MITF levels, others show low MITF expression." (PMID 39562548, 2024). "These hallmarks coincide with the modulation of several melanoma-associated signalling pathways, such as the MAPK pathway and MITF, which stimulate growth." (PMID 39594467, 2024). "To determine the effect of MITF-sl on subcellular localization, we used dox-inducible A375P melanoma cells overexpressing MITF-Flag fusion proteins and performed cellular fractionation." (PMID 39169200, 2024). "In contrast, the levels of the receptor tyrosine kinase AXL a known marker of acquired resistance to targeted therapies in melanoma, underwent an opposite trend of modulation as compared to mir-579-3p and MITF." (PMID 38472212, 2024). "STAT3 antagonizes MITF and drives melanoma metastasis in vivo suggesting a potential STAT3-mediated dedifferentiation in response to GRASLND downregulation." (PMID 39398277, 2024). "Research has demonstrated that MITF can enhance the lifespan of melanoma cells by utilizing various anti-apoptotic pathways." (PMID 38534309, 2024). "In order to demonstrate a direct transcriptional role of MITF on IDH1 and NNT, chromatin immunoprecipitation (ChIP) with anti-MITF antibodies in UACC257 melanoma cells was performed." (PMID 39277608, 2024). "Since MITF controls the expression of genes required for melanin synthesis, including tyrosinase, future elucidation of the specific effects between sulfation and melanogenesis may provide new insight into the complex biology underlying melanogenesis and melanoma." (PMID 38892038, 2024). "The expression of PRDX1 was higher than that of PRDX2 in melanoma cells and more similar to that of MITF than that of PRDX2." (PMID 38790661, 2024). "In particular we show that miR-579-3p is specifically deregulated in BRAF-mutant melanomas and that its expression levels mirror those of MITF." (PMID 38472212, 2024).
melanoma (continued). "MITF, commonly expressed in melanomas, plays a major part in transformation and progression, as it regulates the progression of TYR." (PMID 39519055, 2024). "This bioenergetic switch is specific to melanoma and is mediated by the melanocyte lineage factor MITF." (PMID 39501277, 2024). "Analysis of DNA methylation in melanoma cell lines has revealed a large group of hypermethylated genes, one of which includes the MITF gene." (PMID 38275910, 2024). "First, mRNA levels of NNT were downregulated and upregulated after knockdown and overexpression of MITF in UACC257 melanoma cells, respectively." (PMID 39277608, 2024). "Accordingly, melanoma spots of the pigmentation type uniquely express module D, which collects genes of the MITF-program active in melanocyte-like tumor cells assigned as type 1." (PMID 38785552, 2024). "The same results were observed when the MITF-WT, MITF-sp, and MITF-sl proteins were overexpressed in the 501Mel and SKmel28 melanoma cell lines." (PMID 39169200, 2024). "This clearly indicates that increased PD-L1 expression following IFNγ treatment and MITF knockdown, as well as the crosstalk between IFNγ and MITF expression in melanoma cells, is context-dependent." (PMID 39736644, 2024). "Indeed, whether some studies, in concordance with our data, have demonstrated that MITF low levels are associated with the acquisition of resistance to targeted therapies in melanoma, others have reported that MITF can act as driver of reversible non-mutational drug-tolerance." (PMID 38472212, 2024). "To functionally validate the bioinformatic findings, we next investigated the role of MITF in protecting melanoma cell lines from oxidative stress in vitro." (PMID 39277608, 2024). "We have shown here that knockout of either Rab7a or TPC2 in melanoma lines, in particular those that express high levels of MITF result in similar phenotypes i.e., reduction of proliferation, migration, invasion, and tumor growth in vitro and in vivo." (PMID 39562548, 2024). "Based on transcriptomic data, the AXL and MITF subpopulations have been identified in melanoma and play a major role in tumor heterogeneity, as shown in our and other’s data." (PMID 39697983, 2024). "β-Catenin is directly dependent on GSK3β phosphorylation for its degradation, and it is a known regulator of melanoma cell growth, with MITF as a critical downstream target." (PMID 39562548, 2024). "Tumor cells in melanoma show positivity for S-100, HMB-45, vimentin, Melan-A, tyrosinase, and microphthalmia-associated transcription factor (MITF)." (PMID 39280438, 2024). "Studies on melanoma cells expressing high versus low MITF have shown that dedifferentiation has complex immunological implications." (PMID 39736644, 2024). "Changing of expression of the Microphthalmia-associated Transcription Factor (MITF) and the POU domain transcription factor BRN2 (POU3F2) have already been linked to the metastatic mechanism of phenotype switching in malignant melanoma." (PMID 38773108, 2024). "MITF acts as a “rheostat” and is considered as one of the key regulators of melanoma phenotype switching." (PMID 38419052, 2024). "Our findings are in line with studies indicating that C/EBPβ, which is activated by exogenous ceramides, represses MITF transcription in melanoma." (PMID 39136013, 2024). "•Our study shows that MITF+ melanoma subpopulations, are more efficiently targeted by immunotherapy than AXL+ subpopulations." (PMID 39697983, 2024). "Here, we show that MITF regulates a global antioxidant program that increases survival of melanoma cell lines by protecting the cells from reactive oxygen species (ROS)-induced damage." (PMID 39277608, 2024). "Here, we show that MITF drives a global ROS clearance program in melanoma by transcriptionally regulating multiple redox genes that contribute to the regulation of cellular ROS defense mechanisms." (PMID 39277608, 2024).